DDR1 (discoidin domain receptor tyrosine kinase 1)
Diseases named in the same sentence as DDR1 in open-access papers (continued):
Sharing a sentence is not in itself a finding about the gene and the disease.
cancer (continued). "If DDR1-IN-1 is a new necroptosis inducer, as we report here, DDR1-IN-1 may exert an additive or synergistic activity when combined with other anti-cancer agents." (PMID 40025071, 2025). "In addition to its role in regulating cancer cell EMT traits, DDR1 has recently been identified as a key regulator of cancer cell dormancy." (PMID 40563472, 2025). "Notably, cancer cell-derived type III collagen autonomously triggers DDR1 activation, which subsequently enhances STAT1 expression." (PMID 40563472, 2025). "Abnormally high DDR1 expression has been observed in various cancers, including BC." (PMID 40105492, 2025). "Growing evidence indicates that DDR1 is pivotal in cancer progression." (PMID 40456688, 2025). "DDR1 is a critical driver of tumorigenesis, contributing through both its intracellular kinase activity and extracellular non-enzymatic functions, positioning it as an important target for cancer therapy." (PMID 40713963, 2025). "The authors hypothesize that recombinant humanized type III collagen possesses bioactive properties that can inhibit cancer cell activity, with a specific focus on discoidin domain receptor 1 (DDR1) signaling." (PMID 40283137, 2025). "Inhibition of DDR1 has been shown as an anti-cancer strategy in multiple cancer types." (PMID 40025071, 2025). "DDR1 plays a pivotal role in promoting cancer cell survival." (PMID 40563472, 2025). "DDR1 levels are also significantly upregulated in ovarian and gastric cancers." (PMID 40105492, 2025). "However, DDR1’s comprehensive role across diverse cancers and its therapeutic potential in immune-resistant tumors remain poorly defined." (PMID 40869052, 2025). "Therefore, inhibiting DDR1 signaling by small molecules has been proposed as an intervention for cancers." (PMID 40025071, 2025). "It is likely that DDR1 is connected to a complex and dynamic signaling network, and the signaling pathway that is dominantly activated within this network is highly context-dependent and cancer type-specific." (PMID 40456688, 2025). "In contrast, DDR1 degraders, by promoting the proteasomal degradation of DDR1, offer a more comprehensive therapeutic strategy, effectively eliminating both its enzymatic and scaffold functions and providing a more potent approach for cancer treatment." (PMID 40713963, 2025). "Collagens primarily signal to cancer cells in cancers by binding to the DDR1/2 receptors." (PMID 40025071, 2025). "Additionally, the downstream signaling of DDR1, as evidenced by reduced pAKT levels, was significantly decreased in the NSC632839-treated group, further highlighting its potential as a therapeutic strategy for DDR1-positive cancers." (PMID 40713963, 2025). "Increased DDR1 expression has been shown in different human cancers." (PMID 38308500, 2024). "Taken together, these data indicate that DDR1 expression is dysregulated in various cancers versus adjacent normal tissues and may serve as an oncogene or suppressor in these cancers." (PMID 37031216, 2023). "As it happens with collagen, DDR1 also has paradoxical and context-depending roles in cancer." (PMID 37284199, 2023). "We first assessed the expression and prognostic significance of DDR1 across cancers." (PMID 37031216, 2023). "We found that DDR1 was expressed at high levels in most cancers." (PMID 37031216, 2023). "Furthermore, DDR1 expression was positively correlated with the expression of m6A-, m5C-, and m1A-related genes in most cancers, including HNSC, BLCA, LIHC, and THCA." (PMID 37031216, 2023). "Therefore, we conducted a pan-cancer analysis of DDR1 in 33 different cancers based on the data from the most comprehensive databases also explored the expression of DDR1 in ccRCC, BCa, and PCa cells for the first time." (PMID 37031216, 2023). "Moreover, DDR1 expression is associated with the expression of MMR gene and with MSI, TMB, and immune cell infiltration across different cancer types." (PMID 37031216, 2023).
cancer (continued). "For example, overexpression of DDR1 enhances integrin matrix adhesion in human embryonic kidney cells and in human and mouse fibroblasts, and high levels of DDR2 enhance integrin activation in cancer-associated fibroblasts in mice." (PMID 37405383, 2023). "Moreover, we also investigated the expression of DDR1 in different cancer cell lines based on the CCLE database." (PMID 37031216, 2023). "Therefore, we aimed to explore the prognostic value of DDR1 in 33 cancer types and investigate its potential immune function." (PMID 37031216, 2023). "Our results show that DDR1 also plays a vital role in cancer immunity." (PMID 37031216, 2023). "Finally, we used the CancerSEA database and GSEA analysis to address the specific function of DDR1 across different cancers." (PMID 37031216, 2023). "We also analyzed the correlation between DDR1 and B cells and NK cells in 33 types of cancer." (PMID 37031216, 2023). "It was reported that DDR1 is involved in the development of cancer and fibrotic diseases." (PMID 36925653, 2023). "In addition, the Kaplan–Meier plotter database was also applied to evaluate the prognostic relevance of DDR1 expression levels in various cancers." (PMID 35935941, 2022). "Studies performed on cancer cells suggest that microRNAs negatively regulate DDR1 expression." (PMID 36249782, 2022). "Therefore, TIMER database was further applied to investigate the effect of DDR1 on the infiltration status of various TIICs in 39 cancer types and subtypes." (PMID 35935941, 2022). "Since blocking DDRs kinase activity emerged as an attractive therapeutic option in cancer, inflammatory, and fibrotic diseases, significant effort has been made to identify potent and selective DDR1 inhibitors." (PMID 36249782, 2022). "However, in TNBC cell lines 4T1 and MDA-MB-231 cells, TM4SF1 promotes cancer stem cell traits mechanistically by coupling DDR1 to PKCα and augmenting JAK-STAT signaling." (PMID 35153775, 2022). "Subsequently, the cancer prognosis was investigated in relation to DDR1 expression." (PMID 35935941, 2022). "Thus, DDR kinase inhibitors have been generated in the last decade and clearly show efficient inhibition of DDR1-mediated biological effects in animal models of cancer." (PMID 36249782, 2022). "In addition, they demonstrated that DDR1 activation triggered inflammatory signaling and that inhibiting this signal transduction suppressed cancer cell growth." (PMID 36613638, 2022). "According to the immunohistochemical scores listed inTable 2, the DDR1 positive rate was 100% (34 of 34) in poorly differentiated carcinoma tissues, 76% (57 of 75) in moderately differentiated, and 29.4% (5 of 17) in highly differentiated carcinoma tissues." (PMID 35593476, 2022). "In this study, we investigated whether cancer cells exploit collagen-DDR1 signaling to communicate with other stromal cells and modulate the TME to promote PDAC progression and metastasis." (PMID 34237033, 2021). "As no pharmacological approach is available to specifically target the IR-A in cancer, we evaluated whether DDR1 targeting could be alternatively used as a strategy to inhibit IR-A-driven metabolic reprogramming in BC cells." (PMID 34206590, 2021). "In addition to their growing usefulness in cancer therapy, DDR1/2 inhibitors are also useful in the treatment of various inflammatory conditions." (PMID 34827669, 2021). "DDR1 and DDR2 dysregulation has been linked to multiple forms of cancer." (PMID 34207360, 2021). "DDR1 is a critical driver of a mesenchymal and invasive cancer cell PDAC phenotype." (PMID 34237033, 2021). "Cancer cells induce CXCL5 and cause NET formation through the DDR1/PKCθ/NF-κB signaling pathway." (PMID 34237033, 2021). "Emerging studies have demonstrated the role of DDR1 in cancer progression and metastasis." (PMID 33888679, 2021). "However, relative to normal-matched tissue, the percentage of cases with higher membranous DDR1 expression was significantly lower in high vs. low GS cancers." (PMID 34548097, 2021).
cancer (continued). "Targeting DDR1 reduces neutrophil-mediated cancer cell invasion." (PMID 34237033, 2021). "In addition, heat treatment of NCCM harvested from DDR1 intact cancer cell/collagen I/neutrophils results in a reduction of cancer cell invasion, further suggesting that a secreted protein is responsible for the observed effect." (PMID 34237033, 2021). "Because cancer stem-like cells (CSCs) disseminated into the host organs likely function as ‘seeds’ of colonization, we asked whether DDR1 maintained the CSC traits." (PMID 33976105, 2021). "Notably, discoidin domain receptor 1 (DDR1), a collagen receptor often dysregulated in cancer, is involved in a functional crosstalk and feed forward loop with both the IR-A and the insulin like growth factor receptor 1 (IGF1R)." (PMID 34206590, 2021). "Throughout this review, we discussed the biological roles DDRs, their relation to different human diseases, mainly for cancer, and the medicinal chemistry approaches used in the journey of development of DDR1 and DDR2 kinase inhibitors since the discovery of these targets." (PMID 34207360, 2021). "Although ERK1/2, EGFR, or even DDR1 are known as targets to interfere with cancer development and malignancy in oncology for many years, the combined inhibition of these targets offers a novel treatment option in a synergistic manner, especially relevant for TNBC cells." (PMID 32668815, 2020). "As nuclear YAP1 can form a β-catenin transcription complex that is essential for the transformation and survival of β-catenin-driven cancer, we propose that DDR1 supports metastatic development in a collagen-rich environment via a BCR- and PEAK1-dependent mechanism." (PMID 32117772, 2020). "In cancer, for instance, premalignant and fully malignant carcinoma cells can express DDR1." (PMID 33014862, 2020). "How DDR1 oncogenic activity is induced in human cancer is not clear, because DDR1 is not frequently mutated." (PMID 32117772, 2020). "DDR1 is also reported to be involved in fibrotic modeling and cancer progression." (PMID 32668815, 2020). "The discoidin domain receptor-1 (DDR1) is a non-integrin collagen receptor recently implicated in the collective cell migration of other cancer types." (PMID 32244515, 2020). "Indeed, signaling triggered by both TMPRSS4 and DDR1 in cancer cells activate common pathways, including phosphorylation in ERK1/2 and AKT depending on the cellular context." (PMID 31659178, 2019). "The results showed DDR1 staining was positive in 94% (94/100) of cancer samples." (PMID 31116512, 2019). "Based on the hypothesis that these cooperative genes could be consistently co-expressed in tumors, we searched for TMPRSS4-correlated genes in publicly available genomic data and identified DDR1 among other genes related to cancer cell-ECM interaction." (PMID 31659178, 2019). "This hypothesis is in line with results obtained in carcinoma cells, in which the DDR1-driven down-modulation of myosin contraction in the core of clusters is required for collective migration." (PMID 29643414, 2018). "For example, DDR1 was shown to either promote or counteract integrin α2β1-mediated signaling in different contexts and to bind and activate Notch1 promoting survival of cancer cells." (PMID 28536691, 2017). "DDR1 was shown to be pro- or anti-tumorigenic in different types of cancer." (PMID 28536691, 2017). "In these cells, DDR1 through its interaction with the cell polarity regulators Par3 and Par6, induces a decrease in actomyosin contractility and thereby enables collective cancer cell invasion." (PMID 27014069, 2016).
cancer (continued). "In fact, both IGF-IR and DDR1 are overexpressed in various malignancies, and may sustain epithelial-to-mesenchymal transition, invasion, metastases, as well as cancer resistance to therapies." (PMID 26655502, 2016). "Indeed, StarBase Pan-Cancer analysis showed a significant inverse correlation between miR-199a-5p and DDR1 expression in 8/14 cancer histotypes." (PMID 26655502, 2016). "Taken together, these data strongly suggest that paracrine/autocrine IGFs production in cancer may result in increased DDR1 expression through the activation of a PI3K/AKT/miR-199a-5p pathway." (PMID 26655502, 2016). "Next, we evaluated whether miR-199a-5p was negatively correlated with DDR1 or with IGF-IR in a panel of human cancer histotypes." (PMID 26655502, 2016). "Furthermore, collagen activated DDR1 triggers diverse pro-survival pathways toward anti-apoptotic, proliferative and aggressive features in cancer cells." (PMID 27384677, 2016). "The depletion of DDR1 led to disrupted collective cancer cell invasion, which could be reversed by adding a ROCK inhibitor." (PMID 26872368, 2016). "DDR1 may be down-regulated in certain types of cancers, thus promoting focal adhesion and stress fibre formation, and resulting in the endocytosis of E-cadherin." (PMID 27824116, 2016). "The observed crosstalk between the IGF-IR and DDR1 may have, therefore, important implications in development and cancer progression." (PMID 26655502, 2016). "In addition to epithelial and carcinoma cells, short-term activated human T cells also express DDR1 and the blocking recombinant receptor DDR1:Fc reduces their migration across collagen gel-coated transwells." (PMID 27391444, 2016). "In fact, DDR1 overexpression has been reported in several malignancies, where it may have a role in epithelial-mesenchymal transition and cancer progression." (PMID 25840417, 2015). "Since DDR1 plays a role in stabilizing cell-cell junctions through E-cadherin, it may play a valuable role in regulating collective cell migration possibly in cancer metastasis." (PMID 25369402, 2014). "Furthermore, pan-cancer analysis demonstrated a significant inverse correlation between the expression of DDR1 and immune receptors across multiple malignancies, with PAAD exhibiting the most pronounced downregulation of immune receptors, as visualized by the deepest blue coloration in the heatmap." (PMID 40869052, 2025). "Moreover, DDR1 expression reduces the sensitivity to chemotherapy, which may lead to cancer recurrence." (PMID 40603853, 2025). "Moreover, COL4A6 promoted cancer cell sensitivity to cisplatin via DDR1/NF-κB pathway activation." (PMID 40603853, 2025). "Tissue collagen may be a key driver of DDR1 expression in cancer cells." (PMID 40603853, 2025). "Therefore, it seems that DDR1 can influence DARPP-32 isoforms in cancers." (PMID 38308500, 2024). "In summary, these results suggest that DDR1 may serve as a potential therapeutic target in cancers." (PMID 37031216, 2023). "Interestingly, with regard to different cancer types and even subtypes, DDR1 expression may be inversely correlated to prognosis." (PMID 35935941, 2022). "Moreover, DDR1 has been shown to promote collective cancer cell invasion by coordinating the Par3/Par6 cell-polarity complex; however, whether this is via an integrin dependent or independent mechanism is unclear." (PMID 35309920, 2022). "In other cancers, DDR1 expression could also have a prognostic implication." (PMID 35205677, 2022). "Finally, we tested whether DDR1-mediated NET-induced cancer cell invasion was through the PKCθ/SYK/NF-κB axis." (PMID 34237033, 2021). "Whether DDR1 can affect metabolic reprogramming of cancer cells is currently unknown." (PMID 34206590, 2021).
cancer (continued). "Hence DDR1 is considered a promising target for cancer therapy." (PMID 31116512, 2019). "As ABL is not mutated in this cancer, we speculated the involvement of DDR1, the other major target of this inhibitor that was identified using a chemical proteomic approach." (PMID 29438985, 2018). "Moreover, DDR1 colocalizes with linear invadosomes which correlate with the ability to metastasize in cancer cells and may regulate their formation and the ability of matrix degradation through Tuba and Cdc4214." (PMID 28368050, 2017). "Therefore, our present data may suggest that the activation of the IGF-IR/AKT/miR-199a-5p/DDR1 pathway may play a relevant role in cancer EMT, cell stemness, invasion and metastasis." (PMID 26655502, 2016). "However, DDR1 can also promote single cell migration by up-regulating N-cadherin, suggesting that its role in cancer cell migration could be context or cell type dependent." (PMID 26872368, 2016). "Thus, we investigated whether a functional cross-talk between the IGF-IR and DDR1 exists and plays any role in cancer progression." (PMID 25840417, 2015). "Thus, DDR1 expression appears to be elevated in a variety of human cancers." (PMID 21541037, 2011). "Stage-stratified correlation analysis of fourteen pathway genes revealed profound divergence between DDR1 and DDR2; DDR1 correlations remained weak across all stages, while DDR2 correlations strengthened 2.59-fold from normal to carcinoma." (PMID 41828724, 2026). "The identification of USP7 as a key regulator of DDR1 and the potential development of USP7 inhibitors open new therapeutic avenues for targeting the USP7-DDR1 axis in cancer treatment." (PMID 40713963, 2025). "The DDR family (DDR1/DDR2) can be activated by various collagen types, influencing diverse cancer cell behaviors." (PMID 40563472, 2025). "Our pan-cancer screening revealed that PDAC shows concurrent DDR1 over-expression, low immune/stromal scores, and dismal prognosis—features aligned with DDR1’s known roles in collagen remodeling." (PMID 40869052, 2025). "Multiple targets involved in collagen synthesis modulation—such as MMP, LAIR-1, DDR1, HSP47, and LARP6—have been identified sparking interest in collagen’s untapped potential in cancer immunotherapy." (PMID 40721833, 2025). "Findings from the GSE6764 database revealed a common overexpression of both ANKRD17 and DDR1 in advanced stage HCC cases, particularly in patients with cancer that has spread to lymph nodes or other organs." (PMID 40458187, 2025). "For mortality attributed to cancer, 28 proteins were statistically significant, with SERPINA3 showing the largest effect (2.79), alongside DDR1, LRG1, and GDF15 as the top contributors." (PMID 41270070, 2025). "DDR1 expression was negatively correlated with TAPBP (MHC-related gene) in KICH, PCPG, SARC, and THCA, while positively correlated in other 19 cancers." (PMID 37031216, 2023). "DDR1 displays sustained activation upon interaction with collagen and the high expression level of DDR1 is significantly correlated with poor PDAC survival, implying that collagen/DDR1 mediated signaling would play an important role in cancer progression." (PMID 38071340, 2023). "We used co-expression analysis to analyze the relationship between DDR1 expression and RNA methylation-related genes, mismatch repair (MMR) gene, immune-related genes, and drug sensitivity in different cancers." (PMID 37031216, 2023). "Here, we discussed the roles of DDR1 and DDR2 in premalignant liver diseases, primary HCC and metastatic liver cancer derived from several other cancer types." (PMID 37007062, 2023).